LEP (leptin)
Diseases named in the same sentence as LEP in open-access papers (continued):
Sharing a sentence is not in itself a finding about the gene and the disease.
Obesity (continued). "We hypothesize that skeletal muscle SOCS3 contributes to obesity and insulin resistance by antagonizing leptin and insulin signaling." (PMID 23115649, 2012). "In obesity, the release of adipokines such as leptin, resistin, and adiponectin can be altered." (PMID 22645452, 2012). "The current model suggests that obesity in humans is due to a desensitization to leptin." (PMID 22263109, 2012). "At least in the widely used C57Bl/6 mouse, high-fat feeding, even in the absence of dietary carbohydrate, leads to obesity and an associated increase in leptin levels as well as distinct insulin resistance." (PMID 22838969, 2012). "We propose a model where chronic over-stimulation of the leptin-LepRb signaling pathway in arcuate neurons may play a role in development of arcuate leptin resistance and diet-induced obesity, possibly via elevation of SOCS3 expression." (PMID 22276206, 2012). "By illustrating how astrocytic leptin signaling facilitates leptin transport across the in vitro BBB and attenuates the development of diet-induced obesity in mice, we have deduced a novel role for the astrocytic leptin system in gliovascular and metabolic coupling." (PMID 22530983, 2012). "Such state in human medicine is called leptin resistance, the failure, in obese individuals with elevated leptin levels, for suppressing feeding and mediating weight loss due to LEPR polymorphisms associated with food preferences and obesity." (PMID 22629144, 2012). "The physiological role of leptin is very complex; it could be an important mediator of the relationship among obesity, overweight, and atherosclerosis." (PMID 22547903, 2012). "Leptin 24-hour levels were significantly lower in obese compared with nonobese adolescent girls, suggesting that blunted circadian variation may play a role in leptin resistance and obesity." (PMID 22474595, 2012). "Perhaps the most important finding in hunting obesity gene occurred in 1994, when Zhang and coworkers demonstrated for the first time that an adipose-derived hormone, leptin, plays a key role in regulating intake and energy expenditure, including appetite and metabolism." (PMID 22474595, 2012). "Obesity was also associated with increased expressions of angiogenesis-related proteins, in particular, angiogenin, endoglin, endostatin, endothelin-1, IGFBP-3, leptin, MMP-3, PAI-1, TIMP-4, CXCL16, platelet factor 4, DPPIV and coagulation factor III." (PMID 22748184, 2012). "The discovery of leptin represents a huge step in the study of obesity." (PMID 22474595, 2012). "Interestingly, central leptin administration and gene therapy has successfully improved energy homeostasis as well as prevented diet-induced obesity and metabolic syndrome in mice." (PMID 22518191, 2012). "Moreover, the androgen response to human chorionic gonadotropin (hCG) stimulation is impaired in obese men, and leptin is the best hormonal predictor of reduction to androgen response related to obesity." (PMID 22235202, 2012). "Second, studies reported that the adipocyte hormone adiponectin and leptin, which can regulate podocyte function, may play an important role in the development of obesity-related albuminuria." (PMID 23251329, 2012). "A leptin hypothesis linking mood disorder and obesity, two largely overlapping conditions at the population level, has been formulated." (PMID 22235252, 2012). "Resistant to the effects of leptin, termed leptin resistance, is seen in obesity and aging." (PMID 22675349, 2012). "Brain specific deletion of STAT3 results in leptin resistance and obesity in mice." (PMID 22359610, 2012). "Studies have been provided indicating that higher leptin concentrations may constitute a possible link relating obesity and cancer, particularly colorectal cancer." (PMID 22701472, 2012). "In humans, circulating leptin concentration increases directly with increasing obesity." (PMID 23285260, 2012).
Obesity (continued). "Biosynthesis of leptin in adipose tissue is influenced by insulin, and this may explain the high leptin levels observed in obesity." (PMID 22701472, 2012). "However in mice, chronic activation of the mTOR/S6K pathway by POMC neuron-specific deletion of TSC1, demonstrate leptin resistance, hyperphagia and obesity, presumably due to an alteration of the hypothalamic neurocircuitry of energy balance." (PMID 22291999, 2012). "In CKD the picture is more complicated as the initial development of CKD may be with a background of obesity; and hence raised leptin levels (and leptin resistance)." (PMID 22537670, 2012). "Therefore, we investigated the associations of low serum amylase with plasma insulin levels, and obesity-related parameters, including leptin." (PMID 22748134, 2012). "Briefly, mounting evidence suggests that the leptin to adiponectin ratio is sensitive to states of obesity, T2DM, and MetS and that the ratio is a key clinical determinant of cancer tumorigenesis and/or carcinogenesis with elevated leptin being associated with greater cancer risk and poor outcome." (PMID 23369448, 2012). "Moreover, mice that chronically over-express leptin paradoxically accumulates fat mass with age and exhibit increased susceptibility to HFD-induced obesity." (PMID 22276206, 2012). "BMI underestimates obesity prevalence, especially in women with high leptin levels (>30 ng/mL)." (PMID 22485140, 2012). "Endoplasmic reticulum (ER) stress is a recently identified key mechanism for the development of obesity and leptin resistance and therefore could be a trigger for Ob-R downregulation and suppressed sOb-R generation." (PMID 22545089, 2012). "In recent murine studies, animals missing the leptin-codifying gene developed pronounced obesity." (PMID 23009606, 2012). "Causes and the mechanism of correlation between renal damage with obesity are not well understood, but it is clear that some factors such as insulin resistance, mild inflammation and the action of leptin could be involved." (PMID 24971248, 2012). "In diet-induced obesity, as well as neonatal overfeeding mice, leptin is markedly increased." (PMID 23056561, 2012). "Such downregulation might be a consequence of elevated fasting insulin or leptin levels observed in obesity." (PMID 23162532, 2012). "Since a recent study showed that the significant lowering of leptin impacts long term weight control, the idea of utilizing leptin as a component in the national attack on obesity might be considered." (PMID 22485140, 2012). "Leptin measurements need further study as potentially useful in the management of obesity." (PMID 22485140, 2012). "Overall, the glial leptin system shows robust regulation and plays an essential role in obesity." (PMID 22530983, 2012). "Second, while we might expect this observed reduction in leptin/insulin sensitivity to result in increased dopamine function, analogous to reduced leptin/insulin signals in food-restriction, most studies report decreased dopamine function in obesity." (PMID 22833718, 2012). "Leptin levels rise in response to increased energy deposition as fat mass and in obesity." (PMID 22537670, 2012). "Adipose tissue, which is accumulated in obesity, is a key endocrine organ that produces multiple biologically active molecules, including leptin, adiponectin, resistin, that affect inflammation, and subsequent deregulation of cell function in renal glomeruli that leads to pathological changes." (PMID 22567283, 2012). "The result that over-expression of LepRb in POMC neurons increases body weight in HFD mice is initially surprising, considering the well known anti-obesity effect of the leptin-LepRb system and our recent report showing that expression of LepRb in POMC neurons of Leprdb/db mice reduces body weight." (PMID 22276206, 2012). "SNCG (synuclein gamma) has recently been termed an adipocyte-neuron gene that is coordinately expressed with leptin in human obesity and might promote adipocyte differentiation." (PMID 22369239, 2012).
Obesity (continued). "Leptin resistance programming may be one of the mechanisms that may account for the greater propensity to obesity." (PMID 23189059, 2012). "It is therefore not surprising that failures in the leptin signalling system have been linked to obesity in humans." (PMID 22013440, 2011). "Thus, in the current study, we investigated sex-dependent correlations between the diffusion parameters ADC, FA, λ∥, and λ⊥, and the obesity parameters BMI and blood concentrations of leptin." (PMID 21494606, 2011). "Taking into account their involvement in obesity and apoptosis, the aim of our study was to investigate the balance between circulating levels of 25-hydroxy vitamin D (25(OH)D), leptin, and adiponectin, and PED/PEA-15 protein abundance, in both lean and overweight/obese (o/o) women with PCOS." (PMID 22112520, 2011). "Going back to obesity research for exemplification of this point, it is scientifically desirable that a laboratory-based biochemical intervention in, for example, leptin and insulin interactions in mice, is potentially transferrable to other experimental systems and other disciplinary approaches." (PMID 21276254, 2011). "In the present study, only 4 weeks on a hyperlipidic diet, both continuously and alternated with a chow diet, caused an enhancement in adiposity that was accompanied by an increase in serum leptin concentration, which shows that short periods of hyperlipidic diets can promote obesity." (PMID 21943199, 2011). "Indeed, SH2B1 modulates leptin sensitivity and Sh2b1 knock-out mice develop hyperphagia and obesity." (PMID 22043164, 2011). "Therefore, a reduced ability to synthesise or respond to leptin is likely to lead to a failure to control appetite and reduced expenditure of energy, leading to an increase in weight and, in time, obesity." (PMID 22013440, 2011). "Obesity increases the expression of leptin, a multifunctional peptide produced predominantly by adipocytes which may promote tumor growth." (PMID 21338489, 2011). "Thus, adipose tissue is recognized as a major secretory organ, releasing a variety of adipocytokines (e.g. adiponectin, leptin, resitin and others) which provide the link between obesity, insulin resistance and inflammatory disorders." (PMID 21929808, 2011). "Interestingly, the levels of α-synuclein are also relevant to obesity, as increased α-synuclein is reportedly consistent with increased leptin and obesity." (PMID 20797931, 2011). "Furthermore, study of the leptin gene is of crucial importance for public health, particularly for its role in obesity, as well as for other numerous physiological roles that it plays in mammals." (PMID 22046310, 2011). "However, leptin mimics developed as anti-obesity agents have been unsuccessful to date, due to leptin resistance in obese humans." (PMID 21506921, 2011). "Since visceral fat area was higher in sarcopenic obesity group than single obesity group after correction for age, the difference in plasma leptin between the two groups could be influenced by visceral fat area itself rather than thigh muscle CSA." (PMID 21931785, 2011). "High Ang II levels may deteriorate obesity-related hypertension because of an increased secretion of proinflammatory cytokines, decreased adiponectin secretion and increased leptin production in adipocytes." (PMID 21410966, 2011). "Since it is clear that leptin is a strong candidate as one of the molecules that links obesity to neurodegeneration, and we know that obesity in midlife enhances the risk of AD, the possibility of manipulating leptin levels or leptin signalling in advance of the onset of AD symptoms arises." (PMID 22013440, 2011). "Additionally, our findings are supported by another study which showed that the offspring from enlarged litter sizes had enhanced leptin sensitivity and were protected from obesity." (PMID 21637839, 2011).
Obesity (continued). "Because leptin influences appetite, energy consumption, adipose synthesis, and insulin function, investigators have explored the use of recombinant leptin as a treatment for obesity." (PMID 21526991, 2011). "The IGF-1 is involved in androgen-independent progression of prostate cancer and leptin induces migration in prostate cancer cells, thus obesity-induced hormonal changes may promote tumour progression." (PMID 21266978, 2011). "A survey found adiponectin provided extra-predictive power beyond obesity while leptin did not independently predict the risk of diabetes and IFG in older Chinese adults." (PMID 21909476, 2011). "The SH2B1 gene is for instance an interesting candidate as SNPs at the SH2B1 locus are associated with BMI by GWAS, rare deletions including SH2B1 are associated with a Mendelian form of obesity and inactivation of SH2B1 in mice leads to hyperphagia, leptin resistance and obesity." (PMID 22043165, 2011). "High leptin levels were associated with a more severe asthma suggesting that the link between adipokine leptin and asthma is not restricted to obesity." (PMID 21615949, 2011). "We measured serum leptin, adiponectin, serum amyloid A, keratinocyte-derived chemokine, and lipocalin-2 concentrations because these have a role in insulin resistance, type-2 diabetes, and obesity." (PMID 21314942, 2011). "Obesity may affect bone metabolism directly or indirectly through adipocyte-derived cytokines such as leptin and adiponectin." (PMID 21676245, 2011). "Within this framework leptin appears as one of the candidate molecules that might link obesity and age to neurodegeneration." (PMID 22013440, 2011). "Thus, mice that fail to respond to leptin develop obesity even if fed a diet that restricts calorific intake to normal levels implying that these animals are not expending the energy from their food efficiently." (PMID 22013440, 2011). "Based upon high leptin and low adiponectin levels in obesity, the ability of leptin or adiponectin, respectively, to augment or suppress TF synthesis could imply a mechanistic role of TF in developing inflammatory obesity." (PMID 21941675, 2011). "This recent finding suggested that obesity, per se, is not a sufficient condition to induce knee OA, but that leptin is necessary in the pathophysiology of OA development and progression associated with obesity." (PMID 22046513, 2011). "Variants in or near LEP, POMC, MC4R, and IL-6 genes confer a significant risk to human obesity." (PMID 21390334, 2011). "As obesity is characterized by excessive storage of adipose tissue, adipokine secretion is increased; therefore, the effects produced in the body are altered, and resistance to its effect can be generated, as in the case of leptin." (PMID 21686173, 2011). "Finally, the ratio of leptin-to-adiponectin (L/A), has been reported to represent a better marker for obesity, IR, and MetS than each single adipokine, in particular in female population." (PMID 22112520, 2011). "Because leptin has a certain degree of influence on appetite, energy consumption, adipose synthesis, and insulin function, elevated serum leptin levels are common in human obesity." (PMID 21526991, 2011). "It has been hypothesized that leptin might be a systemic or local factor mediating the metabolic link between obesity and OA and partially accounting for the gender disparity of this disease." (PMID 22046520, 2011). "Increasing evidence suggest leptin signaling could be an important link between breast cancer incidence/growth and obesity." (PMID 21731759, 2011). "The signaling pathway, with increase in leptin due to obesity and decrease in osteocalcin, may help regulate, primary or secondary, these ionic changes." (PMID 22192330, 2011). "However, high levels of leptin have been observed in more common forms of obesity indicating a state of leptin resistance which limits the application of leptin in the treatment of obesity." (PMID 20808936, 2010).
Obesity (continued). "Mutations in the leptin gene (LEP) have been reported to cause severe obesity and may also contribute to the complications associated with obesity." (PMID 20140086, 2010). "In light of this, the resistance to leptin in overweight or obese patients could represent a protective mechanism against the excess pro-thrombotic stimulation produced by obesity-related hyperleptinemia." (PMID 20652043, 2010). "Studies of rodents with genetic abnormalities in leptin or leptin receptors revealed obesity-related deficits in macrophage phagocytosis and the expression of proinflammatory cytokines both in vivo and in vitro, whereas exogenous leptin upregulated both phagocytosis and the production of cytokines." (PMID 20368778, 2010). "In the early stages of obesity, mice develop resistance to leptin delivered peripherally, but not centrally; this has been attributed to downregulation or saturation of the transport system that transports leptin across the blood-brain barrier." (PMID 20613882, 2010). "Similarly, SREBP1, PPARα/γ, NR3H1 and LEP were identified as common regulatory factors for fatty acid metabolism, cholesterol efflux and triglyceride metabolism in zebrafish and mammalian obesity." (PMID 20961460, 2010). "The increased leptin levels observed in OSAHS cannot exclude the possible involvement of leptin in the depressed respiratory response during sleep since studies have not yet examined whether the disease is a leptin-resistant state, like obesity per se." (PMID 21040518, 2010). "The associations between leptin, interleukin (IL)-6, and hip radiographic osteoarthritis (OA) have not been reported, and their roles in obesity-related hip OA are unclear." (PMID 20482813, 2010). "However, in most cases of obesity levels of circulating leptin are high, implying a state of resistance to the weight-reducing effect of leptin." (PMID 20059770, 2010). "In addition, oral supplementation with leptin during lactation protects animals against diet induced obesity and enhances preferences for CHO-rich foods rather than fat-rich foods." (PMID 20796266, 2010). "Therefore, RBP4 and resistin levels appear to better predict obesity and insulin resistance than leptin in our model." (PMID 20633301, 2010). "The result implied that obesity mice accompanied with leptin resistance." (PMID 20482839, 2010). "Moreover, obesity affects the synthesis of adipokines (e.g. leptin, adiponectin and resistin), which operate in a variety of metabolic and immunologic activities, for instance regulating food intake, insulin resistance and inflammation." (PMID 20646281, 2010). "All in all, these results suggest that fetal programming of certain leptin resistance and the resulting hyperleptinemia, in the male offspring of caloric restricted animals, may be critical in the development of obesity." (PMID 20796266, 2010). "However, in common obesity, leptin is increased, which would theoretically be a protective factor against AD." (PMID 21070531, 2010). "The discovery of leptin was considered synonymous to the discovery of the antidote to obesity." (PMID 21040518, 2010). "In addition, increased expression of inflammatory mediators such as TNF-α, PAI-1, and leptin was detected in human obesity." (PMID 20414465, 2010). "Diet-induced obesity causes insulin resistance, whereas leptin improves glucose homeostasis independent of its effects on body weight." (PMID 20613882, 2010). "More recently, the intensity of the debate was fuelled by the hypothesis that HFCS lead to obesity because fructose bypasses food intake regulatory system (insulin and leptin) and favors lipogenesis." (PMID 21050460, 2010). "Data suggest that repeated sleep hypoxemia may promote leptin production independently of the degree of obesity." (PMID 21040518, 2010). "Central resistance to insulin and/or leptin has been proposed as important mechanisms responsible for the dysregulation of energy homeostasis, which may lead to obesity." (PMID 20796266, 2010).